RNU6-414P (RNA, U6 small nuclear 414, pseudogene)
Gene: Small nuclear RNA gene on chromosome 1 (61,816,419 to 61,816,522, forward strand). Ensembl gene ENSG00000200575.
Homologues: Orthologues: chimpanzee U6 (100% identical), macaque U6 (92% identical), dog U6 (88% identical), mouse Gm23507 (88% identical), rat LOC120097649 (84% identical), mouse Gm23847 (82% identical), dog U6 (76% identical), rabbit U6 (70% identical). Paralogues in human: RNU6-12P (89% identical), RNU6-13P (89% identical), RNU6-29P (89% identical), RNU6-32P (89% identical), RNU6-1 (88% identical), RNU6-1094P (88% identical), RNU6-1124P (88% identical), RNU6-1181P (88% identical), RNU6-11P (88% identical), RNU6-16P (88% identical), RNU6-17P (88% identical), RNU6-18P (88% identical), and 1288 more.